NPC1 (NPC intracellular cholesterol transporter 1)
Diseases named in the same sentence as NPC1 in open-access papers (continued):
Sharing a sentence is not in itself a finding about the gene and the disease.
cancer (continued). "In addition, some new cholesterol metabolism molecules, such as SOAT1, SQLE and NPC1, have recently become promising drug targets for cancer treatment." (PMID 38817876, 2024). "Together, this suggests NPC1 as a potential target in this cancer subtype." (PMID 35884604, 2022). "At least in cell-based models, one prominent molecular target of NPC1 within close proximity to the LE/Lys limiting membrane is mTORC1, the master growth regulator commonly upregulated in cancer cell metabolism, promoting anabolic processes that support growth and proliferation." (PMID 35806209, 2022). "In addition, the crosstalk between NPC1 and mTORC1 is further complicated through NPC1 influencing Akt signalling, which is upstream of the mTORC1 complex and frequently activated in human cancers." (PMID 35806209, 2022). "In this review, we will provide an overview of the existing knowledge that implicates the export of LDL-derived cholesterol from LE/Lys mediated by NPC1/2, other cholesterol transporters and related proteins in LE/Lys with cancer cell growth, metastatic behavior and anticancer drug efficacy." (PMID 35806209, 2022). "In the context of cancer, NPC1 activity and function are understudied." (PMID 35884604, 2022). "A number of mechanisms may affect cancer cell comportment in response to NPC1-mediated LE/Lys-Chol transport." (PMID 35806209, 2022). "NPC1 was also upregulated in metastatic estrogen receptor (ER)-negative breast cancer cells, indicating efficient LE/Lys-Chol distribution to support cancer progression." (PMID 35806209, 2022). "Follow-up studies then identified Rab8a to interact with myosin5b to facilitate the docking of LDL-cholesterol-containing vesicles emanating from LE/Lys in an NPC1-dependent manner to the cell surface, stimulating focal adhesion dynamics and migration in A431 carcinoma cells." (PMID 35806209, 2022). "Hence, it is possible that the direct target of leelamine is NPC1, leading to disruption of cholesterol transport in cancer cells." (PMID 28423677, 2017). "Interestingly, NPC1-depleted cancer cells exhibited a slight increase in cell death, and NPC1-depleted ARP-1 cells displayed a swelling phenotype, which is a characteristic feature of pyroptosis, and nigericin (as an inducer of pyroptosis) treatment increased the numbers of swelling cells." (PMID 41013744, 2025). "Several cancer‐related mechanisms in relation to NPC1 could influence leucocyte recruitment." (PMID 39707615, 2025). "Finally, we wanted to determine whether NPC1 inhibitors can be used to treat cancers in combination with first-line chemotherapeutics." (PMID 41013744, 2025). "Hence, future studies still need to resolve if NPC1-dependent cholesterol egress across the LE/Lys membrane contributes to the nutrient input that promotes oncogenic mTORC1 signalling to drive anabolic pathways for cancer growth." (PMID 35806209, 2022). "Consequently, like NPC1 deficiency, elevated AnxA6 levels reduced cholesterol-sensitive caveolae formation, FN secretion and integrin recycling, effectively reducing LDL-inducible migration and the invasion of CHO and A431 carcinoma cells." (PMID 35806209, 2022). "Moreover, eight SARS-CoV-2-required genes had a positive or negative association with the abundance of most immune cell types in different cancer types (FDR < 0.01), among which, the expressions of ACE2 and NPC1 were negatively associated with the abundance of CD8+T." (PMID 35082790, 2021). "Together, these data, characterized for the first time the effect of NPC1 inhibition in TNBC, and proposed a role for this protein in cancer." (PMID 35884604, 2022).
cancer (continued). "The approved anti-inflammatory and cancer management drug, cepharanthine, has been found to inhibit endolysosomal trafficking of LDL and free cholesterol via binding and inhibiting NPC1, subsequently increasing the lysosomal pH." (PMID 34281263, 2021). "ACE2, RAB7A, CCDC22, ATP6AP1, NPC1, and PIK3C3 exhibited a positive relationship with sensitivity of 18 anti-cancer drugs (P < 0.01)." (PMID 35082790, 2021). "In total, we obtained 55 target genes in NPC1, 1, 241 target genes in NPC2, 35 target genes in NPC3 and 251 target genes in non-cancer group by searching the miRWalk 2.0 database." (PMID 29455649, 2018). "To confirm that pyroptosis occurred in NPC1-depleted cancer cells in vivo, we injected negative control (sgNC) or NPC1-depleted (sgNPC1) ARP-1 cells into SCID mice and monitored tumor growth." (PMID 41013744, 2025). "To our knowledge, we are the first to demonstrate that targeting NPC1 in the cholesterol absorption pathway of cancer cells not only can induce pyroptosis but also reduce tumor burden in vivo." (PMID 41013744, 2025). "Although NPC1 expression levels did not demonstrate significant differences across age, gender, weight, race, and cancer stage groups, a trend towards higher NPC1 expression was noted in these patient groups." (PMID 40881173, 2025). "To confirm that NPC1 protected cancer cells from pyroptosis by LDL uptake, we generated a NPC1 knockout (NPC1-KO) ARP-1 and HepG2 cells and reintroduced the wild-type (WT) or P691S mutant (NPC1P691S, which reduces NPC1 cholesterol transport) NPC1 using lentivirus to the NPC1-KO cells." (PMID 41013744, 2025). "NPC1 protects cancer cells from pyroptosis by maintaining cholesterol homeostasis and facilitating LDL-mediated cholesterol uptake, leading to enhanced geranylgeranyl pyrophosphate synthesis for cancer cell survival." (PMID 41013744, 2025). "ACE2, RAB7A, PIK3C3, ATP6AP1, NPC1, and ATP6V1A had a negative association with the sensitivity of 16 anti-cancer drugs (P < 0.05)." (PMID 35082790, 2021). "To investigate whether the protective effect of NPC1 against pyroptosis depends on its function in LDL uptake, we treated cancer cells with U18666A, which is a selective inhibitor that blocks the function of NPC1 protein leading to impaired cellular uptake of LDL." (PMID 41013744, 2025). "Here we describe a mechanism of how cancer cells employ oncogenic growth factor signaling to promote uptake and utilization of extracellular cholesterol via Myeloid Zinc Finger 1 (MZF1)-mediated Niemann Pick C1 (NPC1) expression and upregulated macropinocytosis." (PMID 37420029, 2023). "While a strong connection of NPC1 to lung cancer has not been established at this time, research showed various connections to other cancers and to cancer treatments that could be further explored." (PMID 34281263, 2021). "Future studies will need to unravel how cells coordinate the cholesterol transporter activities of NPC1, LAMP2 and LIMP2 when LDL-cholesterol supply is high and whether the cholesterol-binding activities of LAMPs and LIMP2 are relevant contributors to the pathophysiology of certain cancers." (PMID 35806209, 2022). "The four ARGs RHEB, NPC1, PRK3D, and CLN3 have not been reported in previous studies on HCC or other cancers." (PMID 37370041, 2023).
tumor (17 papers, 2017 to 2025). "In aggregate, we found that increased NPC1 expression correlated with increased tumor grade and potentially linked to the metastatic potential of HCC." (PMID 40881173, 2025). "NPC1 protein in tumors was positively associated with tumor stages in both male and female patients." (PMID 40722778, 2025). "NPC1 protein levels were positively correlated with tumor size in females and tumor grade in males, and were negatively associated with survival time in males, demonstrating sex-specific associations between tumor NPC1 protein levels and tumor size, tumor cell differentiation, and disease outcome." (PMID 40722778, 2025). "Silencing of NPC1 causes significant loss of tumor-promoting capabilities of these cell lines." (PMID 35884604, 2022). "The high expression levels of RAB7A, PIK3C3, ATP6AP1, ATP6V1A, CCDC22, and NPC1 were significantly associated with lower tumor purity of patients with hematologic cancer LAML, while TMPRSS2, PIK3C3, ATP6AP1, and ATP6V1A expressions were obviously correlated with higher tumor purity of KICH patients." (PMID 35082790, 2021). "NPC1 correlated with tumor inflammation and tumor size in women and with survival in men, showing sex-specific associations of NPC1 in HCC, the pathophysiological role of which has to be clarified." (PMID 40722778, 2025). "The consistent connection between increased NPC1 expression and poor survival outcomes warrants further study into NPC1’s role in tumor progression." (PMID 40881173, 2025). "As expected, the level of IgA kappa light chain indicated that tumor burden was lower in the sgNPC1 group, and we observed that cleaved caspase-1 level was increased in NPC1-depleted ARP-1 cells from MM-bearing mouse bone marrow." (PMID 41013744, 2025). "Utilizing flow cytometry to monitor cellular changes within the tumor microenvironment has led us to discover that NPC1 plays a crucial role in the regulation of neutrophil recruitment within the tumor." (PMID 39707615, 2025). "In female patients, NPC1 protein levels in the tumors were significantly higher compared to non-tumor tissues." (PMID 40722778, 2025). "Our work uncovers a novel mechanism by which NPC1 controls cell fate through cholesterol metabolism in tumor cells." (PMID 41013744, 2025). "This study showed that NPC1 promotes liver tumor progression by enhancing the recruitment of neutrophils to the tumor environment." (PMID 40722778, 2025). "In the subcutaneous model, NPC1 knockdown led to a significant reduction in tumor size and weight, while reintroducing NPC1 effectively restored tumor growth." (PMID 39762312, 2025). "To further explore NPC1’s role in both tumor growth and metastasis, we utilized a subcutaneous tumor inoculation model alongside a mouse tail vein metastasis model." (PMID 39762312, 2025). "Overall, our results suggest that NPC1 promotes tumor progression by facilitating neutrophil accumulation." (PMID 39707615, 2025). "We also found that both protein and mRNA levels of NPC1 were significantly elevated in HCC tissues compared with paired non-tumor tissues." (PMID 39762312, 2025). "In solid tumors, immunofluorescence staining showed that NPC1 was co-localized with tumor cells and was highly expressed in HCC and kidney renal cell carcinoma (KRCC)." (PMID 41013744, 2025). "NPC1 protein was higher in male patients with tumor stage pT4 compared to pT1b and was positively related to grading." (PMID 40722778, 2025). "AFP levels were positively correlated with NPC1 protein levels (r = 0.353, p = 0.030) and tumor size (r = 0.316, p = 0.015) but negatively correlated with tumor inflammation (r = −0.294, p = 0.029)." (PMID 40722778, 2025). "NPC1 mRNA expression increased with higher tumor stages in HCC and was further increased in patients with metastasis." (PMID 40722778, 2025). "NPC1 depletion led to a drastic reduction in tumor burden and impaired tumor infiltration into the bone marrow (tumor bed)." (PMID 41013744, 2025).
tumor (continued). "In the tail vein metastasis model, NPC1 depletion resulted in a significant reduction in lung tumor metastases, further supporting NPC1’s critical role in tumor metastasis." (PMID 39762312, 2025). "We then investigated the role of NPC1 in regulating tumor development in vivo using human xenograft mouse models." (PMID 41013744, 2025). "NPC1 protein levels in non-tumor and HCC tissues were determined by immunohistochemistry, and the expression in hepatocytes was scored." (PMID 40722778, 2025). "To validate the therapeutic potential of NPC1, we employed an inducible Npc1 knockout model and AAV8-mediated hepatic knockdown, both of which confirmed the tumor-suppressive effects of NPC1 inhibition." (PMID 39762312, 2025). "Consistent with previous studies, NPC1 protein was increased in HCC tissues compared to non-tumor tissues." (PMID 40722778, 2025). "Since macrophages and neutrophils are the main immunosuppressive cells in the tumor microenvironment, we examined their infiltration in tumor tissues after interfering with NPC1 in tumor cells." (PMID 39707615, 2025). "Of note, the effect of U1866A and posaconazole, an approved antifungal agent, which directly binds NPC1 and blocks endosomal cholesterol trafficking, on tumor cell viability was significantly increased under hypoxia, a central event in renal tumorigenesis." (PMID 38339268, 2024). "The effect of NPC1 on anchorage-independent growth and invasiveness demonstrates regulation of multiple tumor cell-intrinsic properties relevant to the metastatic potential of TNBC." (PMID 35884604, 2022). "We observed that SARS-CoV-2 increased ACE2 and NPC1 expression in normal/tumor tissues or cells of the human respiratory system, similar to one previous report." (PMID 35082790, 2021). "Thirdly, we explored the potential connection between fetal renal cell types and WT samples, and found that some cell clusters had distinct features between tumor and para-tumor samples, such as NPC1, ErPrT and IC2." (PMID 34461918, 2021). "Cell cycle related gene sets were specifically enriched in NPC1, which reflect a typical characteristic of the rapidly proliferating tumor cells, therefore we name this subtype as classical." (PMID 29455649, 2018). "NPC1 protein was significantly more expressed in the tumors than in the non-tumor tissues." (PMID 40722778, 2025). "This led us to hypothesize that NPC1 might regulate tumor progression through the tumor microenvironment." (PMID 39707615, 2025). "We analyzed NPC1 expression across multiple tumor types, with a particular focus on HCC." (PMID 40881173, 2025). "Using three tumor models, we showed that NPC1 promotes tumor growth by suppressing pyroptosis." (PMID 41013744, 2025). "In addition, therapeutic targeting of NPC1 in MYC-driven HCC using AAV8-shNPC1 significantly reduced tumor size and number, with knockdown efficiency validated by Western blotting." (PMID 39762312, 2025). "Notably, the previously work showed that NPC1 has a strong positive co‐expression with several immune‐suppressive genes in tumor tissues." (PMID 39707615, 2025). "This function positions NPC1 as a facilitator of tumor progression and metastasis in HCC." (PMID 39762312, 2025). "Histological analysis further confirmed tumor regression in the Npc1-knockout mice." (PMID 39762312, 2025). "Notably, the data in the Nature article showed that NPC1 and several immune‐suppressive genes are highly expressed in tumor tissues." (PMID 39707615, 2025). "This suggests a potential link between NPC1 expression and tumor aggressiveness." (PMID 40881173, 2025). "In this model, Npc1 knockout significantly reduced tumor sizes and weights." (PMID 39762312, 2025). "Finally, we demonstrated that the NPC1 inhibitor U18666A effectively inhibits tumor growth, supporting its therapeutic potential." (PMID 41013744, 2025). "Positive correlations of NPC1 with tumor size were significant only in female patients." (PMID 40722778, 2025).
tumor (continued). "NPC1 protein was positively related to tumor stage and grading." (PMID 40722778, 2025). "Positive correlations of NPC1 protein with tumor size and negative associations with tumor inflammation were observed only in women." (PMID 40722778, 2025). "In male patients, NPC1 protein levels in the tumors were increased compared to non-tumor tissues." (PMID 40722778, 2025). "In addition, NPC1 knockdown reduced colony formation, migration, and invasion of the cells, suggesting a function of NPC1 in tumor development and metastasis." (PMID 40722778, 2025). "Thus, active derivatives of leelamine or abietic acid maintained lysosomotropic properties, bound to NPC1, and disrupted cellular cholesterol transport as well as availability to retard tumor development." (PMID 28423677, 2017). "Using an inducible Npc1 knockout model with tamoxifen (TAM)-inducible Cre recombinase (ERT2-Cre) in DEN-CCl4-induced HCC model, we confirmed that Npc1 deficiency for an eight-week period significantly reduced tumor burden, tumor number, and liver-to-body weight ratios." (PMID 39762312, 2025). "Moreover, NPC1 depletion led to a significant improvement in the survival of tumor-bearing mice." (PMID 41013744, 2025). "Therefore, it is evident that NPC1 may regulate neutrophil migration to tumor tissues through multiple pathways." (PMID 39707615, 2025). "However, NPC1 expression was strongly increased in tumor tissues in both sexes." (PMID 40722778, 2025). "In our snRNA-Seq data of patient samples CHI3L1 expression was high in the high connectivity score-associated MES1 and AC tumor cell populations, but low in low connectivity score-associated NPC1 and OPC tumor cell populations as well as non-malignant cell types." (PMID 38320988, 2024). "Our findings demonstrate that NPC1 is frequently upregulated and amplified in HCC tumor tissues, with higher expression levels significantly associated with reduced overall survival (OS), progression-free survival (RFS), and disease-free survival (DFS)." (PMID 40881173, 2025). "Our findings demonstrate that NPC1 promotes HCC progression by stabilizing TGFBR1 and facilitating tumor cell migration." (PMID 39762312, 2025). "This conclusion was further corroborated by the examination of mRNA and protein of NPC1 expression, which demonstrated markedly higher levels in Liver Hepatocellular Carcinoma (LIHC) tumor tissues relative to normal tissues." (PMID 40881173, 2025). "NPC1 can also stabilize transforming growth factor (TGF)-β receptor type-1, thereby increasing the tumor-promoting activities of TGF-β." (PMID 40722778, 2025). "Consistent with the DEN-CCl4 model, hepatic Npc1 knockout inhibited TGF-β signaling and tumor progression in the MYC-driven HCC model." (PMID 39762312, 2025). "NPC1 protein in the HCC tissues positively correlated with the UICC score (r = 0.346, p = 0.008) and tumor size (r = 0.316, p = 0.015)." (PMID 40722778, 2025). "It was found that the fraction of NPC1, PTA, ErPrT and IC2 was significant higher in tumor samples than that in para-tumor samples, suggesting that the characteristics of these cell types tended to be similar to some tumor derived cells in WT." (PMID 34461918, 2021). "Previous studies have shown that the absence of NPC1 in tumor cells leads to cholesterol accumulation within the cells, reducing cholesterol levels in the tumor microenvironment." (PMID 39707615, 2025). "This shows that the increase in NPC1 protein levels in females with larger tumor sizes is not related to a worse outcome." (PMID 40722778, 2025). "In male patients, tumor NPC1 protein levels were not related to tumor size but were negatively correlated with survival time." (PMID 40722778, 2025).